HGF (hepatocyte growth factor)
Diseases named in the same sentence as HGF in open-access papers (continued):
Sharing a sentence is not in itself a finding about the gene and the disease.
glioblastoma (continued). "Significant differences between glioblastoma samples and healthy controls were observed for angiopoietin, follistatin, HGF, IL-8, PDGF-BB, PECAM-1 and leptin, with specificity ranging from 59–81% and sensitivity from 40–88%, while infrared-spectroscopy reached 100% sensitivity and 87.5% specificity." (PMID 33316976, 2020). "It has been demonstrated that MET and its ligand HGF play a critical role in the proliferation, survival, migration, invasion, angiogenesis, stem cell characteristics, and therapeutic resistance and recurrence of glioblastomas." (PMID 31221203, 2019). "Our studies suggest that development of bivalent anti-MET immuno-reagents may hold a promise to target and remove the MET proteins from glioblastoma cells or other cancer cells that possess high HGF-induced recycling activity of MET." (PMID 30760737, 2019). "Thus, we testify that paeoniflorin inhibits HGF-mediated migration and invasion in glioblastoma cells." (PMID 30886866, 2019). "Moreover, the HGF/c-Met has been demonstrated that it highly expressed in glioblastoma and can facilitated glioblastoma malignant phenotype, such as promoting proliferation, antiapoptosis, strengthening migration, and invasion." (PMID 30886866, 2019). "Of these, the HGF/cMET pathway has seemed an attractive target as it has been shown to operate in many tumors, for example, preclinical studies in glioblastoma and pancreatic neuroendocrine tumor models have shown that MET inhibitors can overcome resistance to anti-VEGF therapy." (PMID 29228696, 2017). "However, the functional interactions between TGF-β family members and HGF/c-MET signaling in glioblastoma remain uncharacterized." (PMID 29238047, 2017). "A number of reports indicated paracrine secretion as paramount to glioblastoma growth, with ligands such as TGFα, IL-6, ΙL-8, HGF and heparin binding EGF playing central role, further supporting the hypothesis." (PMID 27004406, 2016). "Finally Reznik and coworkers demonstrated that HGF stimulation of glioblastoma cells induces EGFR activation via new transcription of EGFR ligands." (PMID 25884419, 2015). "Importantly, interference with cMet signaling, either using ribozymes targeting HGF or cMet, or a cMet-targeting small molecule, inhibits glioblastoma tumor growth in vivo." (PMID 22966858, 2012). "A recent study has also indicated that HGF levels in cerebrospinal fluid could be of prognostic value for predicting the mortality and recurrence of glioblastoma." (PMID 22741575, 2012). "To start dissecting the signaling mechanisms that are mediated by RhoG in glioblastoma, we first examined whether RhoG is activated by HGF (hepatocyte growth factor, also known as scatter factor)." (PMID 22966858, 2012). "HGF is the most potent chemotactic factor known for glioblastoma cells." (PMID 22966858, 2012). "The autocrine HGF-Met dependence of U87 MG is consistent with Met as a functional marker of a glioblastoma stem cell phenotype and the well-documented frequency of functional HGF-Met signaling in GBM." (PMID 36672409, 2023). "Contrary to the concern that bivalent antibodies may activate the targeted RTKs, in this report, we found that glioblastoma cells have an unusual high activity of HGF-induced MET receptor recycling with very few MET molecules get downregulated after HGF stimulation." (PMID 30760737, 2019). "Therefore, some efforts targeting HGF/c-Met have been took to cure the glioblastoma." (PMID 30886866, 2019). "We therefore examined whether RhoG mediates HGF-induced Rac1 activation in glioblastoma cells." (PMID 22966858, 2012). "The HGF/MET pathway is potentially involved in all these processes, and there is strong support from preclinical studies for targeting this pathway in glioblastoma." (PMID 36915128, 2023). "HGF/c-MET signaling is a significant driver of glioblastoma (GBM) growth and disease progression." (PMID 37162666, 2023).
glioblastoma (continued). "HGF/MET signaling is also involved in crosstalk with EGFR HER3 and EGFRvIII, which can lead to enhance activation of oncogenic signaling in glioblastoma." (PMID 35935338, 2022). "Recent studies have found that the interaction between the HGF/MET signaling pathway and other signaling pathways play a profound and significant roles in the pathogenesis of glioblastoma." (PMID 35935338, 2022). "We focus on the role of HGF/MET in the following primary malignant brain tumors: astrocytomas, glioblastomas, oligodendrogliomas, ependymomas, and embryonal central nervous system tumors (including medulloblastomas and others)." (PMID 33066121, 2020). "It competes with HGF for binding to MET and has been demonstrated to inhibit glioblastoma growth in preclinical testing." (PMID 33066121, 2020). "In our present research, HGF induced phosphorylation of c-Met and activates the RhoA/ROCK signaling in glioblastoma cells." (PMID 30886866, 2019). "HGF/MET signaling has been suggested to be important for cell survival, angiogenesis, and invasion in glioblastoma." (PMID 31245283, 2019). "A number of signalling pathways that include autocrine components, such as TGFalpha/EGF/EGFR, PDGF/PDGFR, HGF/SF and CXCL12/CXCR4 ligand/receptor systems, have been identified in glioma and glioblastoma." (PMID 29149169, 2017). "VEGFC (p < 0.001), HGF (p = 0.014), and CHI3L1 (p = 0.043) RNA expression levels were significantly different between the five glioblastoma locations." (PMID 26637806, 2016). "Compared to cortical glioblastomas, periventricular glioblastomas were characterized by a higher expression of two mesenchymal genes, VEGFC (p = 0.001) and HGF (p = 0.001)." (PMID 26637806, 2016). "In this study, we correlated glioblastoma locations with the expression of five mesenchymal genes (VEGFC and its receptor FLT4, HGF and its receptor MET, and CHI3L1) and five proneural genes (PROM1, NOTCH1, DLL3, PDGFRA, and BCAN)." (PMID 26637806, 2016). "We also observed that RhoG is activated by both HGF and EGF, two factors that are thought to be clinically relevant drivers of glioblastoma invasive behavior, and that RhoG is overexpressed in human glioblastoma tumors versus non-neoplastic brain." (PMID 22966858, 2012). "Here, we show that depletion of RhoG significantly inhibits both HGF- and EGF-stimulated Rac1 activation in glioblastoma cells, demonstrating that RhoG acts upstream of Rac1 in these cells." (PMID 22966858, 2012). "Testing on additional glioblastoma cell lines for migration to HGF and FBS, comparing levels of HGF’s receptor, Met, among them, comparing MEM (provided a positive K+ gradient) versus Dulbecco’s PBS (no K+ gradient), and more extensive testing of chemokinetic effects, are reported here." (PMID 40867621, 2025). "The humanized anti-HGF monoclonal antibody YYB101 can inhibit the growth of tumors in vitro and in situ mouse model of human glioblastoma, Importantly, it can downregulate effective factors of cell molecular including such as p-FAK, p-met, Ki-67, pGab1, MMP2, and uPA/plasminogen." (PMID 35935338, 2022). "There, genes with a higher expression in glioblastoma compared to astrocytoma were VEGFA, 4EBP1, CCL2, PLAU (uPA), CXCL8 (IL8), CXCL10 (IP10), CASP8, HGF, LIF, CD40, CDCp1, TNFRSF11B (OPG), CD274 (PD-L1), IL6, CXCL1, CCL20 (MIP3α), CCL8 (MCP2), CD244, MMP1, TNFRSF9, CXCL6, MMP10, FGF5)." (PMID 35301393, 2022). "Furthermore, the inhibition of HGF-induced migration and invasion and actin cytoskeleton rearrangement involved c-Met-mediated RhoA/ROCK signaling in glioblastoma." (PMID 30886866, 2019). "Of note, MET and its ligand hepatocyte growth factor (HGF) also play critical roles in the proliferation, survival, migration, invasion, angiogenesis, stem cell characteristics, therapeutic resistance, and recurrence of glioblastomas." (PMID 31245283, 2019).
glioblastoma (continued). "MET and its ligand hepatocyte growth factor (HGF) play a critical role in the proliferation, survival, migration, invasion, angiogenesis, stem cell characteristics, and therapeutic resistance and recurrence of glioblastomas." (PMID 31221203, 2019). "Moreover, HGF/MET signaling can induce EGFR and HER-3 activation, leading to enhanced activation of oncogenic signaling in glioblastoma." (PMID 31221203, 2019). "Of note, MET and its ligand hepatocyte growth factor (HGF) play a critical role in the proliferation, survival, migration, invasion, angiogenesis, stem cell characteristics, and therapeutic resistance and recurrence of glioblastomas." (PMID 31245283, 2019). "The humanized monoclonal anti-HGF antibody, YYB-101, suppresses tumor growth in vitro and in an orthotopic mouse model of human glioblastoma; it also downregulates important cellular molecular effectors including p-MET, p-Gab1, p-FAK, MMP2, uPA/plasminogen, and Ki-67." (PMID 31221203, 2019). "Despite the significant role attributed to transforming growth factor (TGF)-β family and hepatocyte growth factor (HGF)/c-MET signaling in glioblastoma pathogenesis, their functional interactions have not been well characterized." (PMID 29238047, 2017). "In vivo, it delayed the growth of U87-MG human glioblastoma cells, which express both MET and HGF." (PMID 28548076, 2014). "Activated by its single ligand, hepatocyte growth factor (HGF), the receptor tyrosine kinase MET is pivotal in promoting glioblastoma (GBM) stem cell self-renewal, invasiveness and tumorigenicity." (PMID 37491377, 2023). "To determine the mechanism responsible for this reduced HGF/MET signaling in oval cells with C3G down-regulation, we search for a potential alteration in MET membrane localization and/or recycling as C3G facilitates recycling and membrane localization of EGFR in glioblastoma (GBM) cells." (PMID 36263169, 2022). "Dysregulation of the HGF/c-MET signaling cascade can lead to tumorigenesis by transforming normal cells into tumor cells and c-MET hyperactivation has been reported in cancers including lung cancer, colorectal cancer, glioblastoma, and acute myeloid lymphoma among others." (PMID 35778602, 2022). "In preclinical models, buparlisib (BKM120), a PI3K inhibitor, has been combined with INC280 (capmatinib), a MET inhibitor, and synergy between the two agents has been observed in PTEN-null glioblastoma cell lines that express hepatocyte growth factor (HGF; data not shown)." (PMID 31776899, 2020). "The HGF/SF:c-MET signaling axis has an important role in the initiation and progression of several aggressive cancers including glioblastoma multiforme (GBM)." (PMID 22511956, 2012). "Thus, our study proved that paeoniflorin could inhibit migration and invasion and actin cytoskeleton rearrangement through inhibition of HGF/c-Met/RhoA/ROCK signaling in glioblastoma, suggesting that paeoniflorin might be a candidate compound to treat glioblastoma." (PMID 30886866, 2019). "Finally, we expanded our study to analyze expression profiles of TGF-β, HGF, and a panel of genes essential for pluripotency in the CD45-/CD31- presumptive tumor cell population isolated from freshly resected tumor tissue of 6 glioblastoma patients at diagnosis." (PMID 29238047, 2017). "PTEN status affected anti-c-MET therapies to glioblastomas in which PTEN protein expression was frequently low or absent, and combining anti-HGF/c-MET therapies with mTOR inhibitors additively inhibited growth of glioblastoma xenografts." (PMID 25098767, 2014). "Importantly, immunohistochemical analyses of human glioblastoma and ex vivo single-cell gene expression profiling of TGF-β and HGF confirm the negative interaction between both pathways." (PMID 29238047, 2017).
myocardial infarction (78 papers, 2007 to 2025). Gross necrosis of the myocardium, as a result of interruption of the blood supply to the area, as in coronary thrombosis. "Consistent with our findings, however, several studies have shown that elevated circulating HGF levels are positively associated with insulin resistance, myocardial infarction, and heart failure." (PMID 41356597, 2025). "The main objective of this study is to evaluate the early prognostic value of measurements of copeptin and HGF at hospital arrival for hospital mortality risk, in patients with acute myocardial infarction." (PMID 35482134, 2022). "Copeptin and hepatocyte growth factor have been associated with poor outcome in patients with acute myocardial infarction." (PMID 35482134, 2022). "In a mouse model of myocardial infarction, HGF-treated mice had thicker left ventricular wall in the late infarct area, suggesting that HGF modulates left ventricular remodeling." (PMID 40041176, 2025). "In the treatment of chronic heart failure following myocardial infarction, hepatocyte growth factor (HGF) is an example of a growth factor that activates endogenous stem cells to achieve therapeutic outcomes." (PMID 41291782, 2025). "In preclinical chronic ischemic models (e.g., porcine myocardial infarction), intramyocardial HGF administration increases capillary density by 30%–40% and improves regional blood flow, as quantified using microsphere perfusion assays." (PMID 41000109, 2025). "Our data highlight a potential role of the heparin-induced HGF peak during the acute phase of myocardial infarction." (PMID 41282338, 2025). "They revealed that by further enhancing the activation of the HGF/c-Met pathway, HGF significantly alleviated apoptosis of cardiomyocytes after acute myocardial infarction in diabetic rats and improved cardiac function." (PMID 36797776, 2023). "BM-MSCs are primed in vivo in a heart with myocardial infarction by genetically engineered MSCs expressing hepatocyte growth factor (HGF-eMSC) that are encapsulated within an epicardially implanted cardiac 3D patch." (PMID 37373454, 2023). "Our objective was to evaluate the cardiac safety and effectiveness of intracoronary (IC) administration of HGF-loaded extended release microspheres in an acute myocardial infarction (AMI) swine model." (PMID 36826582, 2023). "HGF is also shown to promote cardiomyocyte differentiation, proliferation, and regeneration, and to protect from myocardial infarction and/or ischemia/reperfusion injury." (PMID 36293268, 2022). "In our retrospective observational study, we measured hepatocyte growth factor and copeptin in blood samples collected at hospital arrival in patients with acute myocardial infarction; and follow-up them until 1-year." (PMID 35482134, 2022). "For instance, hepatocyte growth factor or vascular endothelial growth factor overexpressing MSCs maximized MSC-based myocardial salvage after acute myocardial infarction." (PMID 35477552, 2022). "Cardiac US-mediated HGF delivery in a rat model of myocardial infarction improved cardiac angiogenesis and left ventricle function." (PMID 34188086, 2021). "Hepatocyte growth factor (HGF) has not only been shown to directly induced angiogenesis following myocardial infarction, but also plays a synergistic role in enhancing the effects of VEGF mediated angiogenesis." (PMID 34639108, 2021). "The cardio-protective effects of MSCs conditioned to overexpress HGF, is also evaluated in a mouse model of myocardial infarction." (PMID 32000804, 2020). "In another investigation aimed at evaluating the cardio-protective effects of MSCs overexpressing HGF in a mouse model of myocardial infarction, umbilical derived-MSCs treated with HGF-conditioned medium were harvested and transplanted." (PMID 32000804, 2020).
myocardial infarction (continued). "Delivery of a hepatocyte growth factor (HGF) plasmid to the myocardium in a canine model of myocardial infarction resulted in increased capillary density as well as reduced infarct size and scar tissue formation." (PMID 31238531, 2019). "Our previous data demonstrate the cooperative effect of VEGF165 and HGF overexpression on induction of angiogenesis and fibrosis reduction evaluated in mouse ischemic limb and myocardial infarction in rats." (PMID 31238604, 2019). "Previous studies have shown a gradual increase in the endogenous concentration of HGF mRNA and its receptors (c-met) for up to one week after myocardial infarct." (PMID 31284593, 2019). "Our previous studies demonstrated that VEGF and HGF-secreting U-Ms (VEGF/U-Ms and HGF/U-Ms) enhanced angiogenesis in a rat myocardial infarction model and mouse hind limb ischemia model." (PMID 30174328, 2018). "Although most of these approaches have aimed to improve treatment of myocardial infarction—by making MSCs more resistant to ischemic environments—HGF-overexpressing MSCs (HGF-MSCs) have also been tested in acute lung injury models." (PMID 29482654, 2018). "This study provides experimental proof of concept for a combined approach using simultaneous delivery of VEGF165 and HGF genes to alleviate consequences of myocardial infarction (MI)." (PMID 29787588, 2018). "Here, we evaluated the combination of cell- and gene-based therapy using mesenchymal stem cells (MSC) genetically modified to overexpress IGF-1 or HGF to treat acute myocardial infarction (AMI) in a porcine model." (PMID 27423905, 2016). "Using an in vivo porcine myocardial infarction model, we analyzed the effectiveness for cardiac repair of heterologous paMSC previously transduced for HGF or IGF-1 overexpression (paMSC-mod)." (PMID 27423905, 2016). "HGF depletion significantly attenuated the inhibitory actions of SHED-CM on myocardial infarct size and apoptosis after I/R." (PMID 26542315, 2015). "HGF depletion significantly attenuated the inhibitory actions of SHED-CM on the myocardial infarct area after I/R." (PMID 26542315, 2015). "Serum levels of HGF increase in patients with a variety of liver diseases as well as in cardiovascular diseases such as acute myocardial infarction, hypertension and congestive heart failure." (PMID 24642599, 2014). "In human patients with acute myocardial infarction (MI), increased secretion of HGF in blood circulation is observed, probably as a consequence of myocardial damage." (PMID 28548070, 2014). "Overexpression of HGF in BM-MSCs enhanced their regenerative effect in acute myocardial infarction, while suppression of HGF expression reduced their efficacy." (PMID 24646687, 2014). "The expression of HGF and its secretion into the blood circulation are promoted during the early phase of myocardial infarction." (PMID 24983946, 2014). "Several studies have revealed that HGF is an endogenous cardioprotective factor, as it protects cardiomyocytes from acute ischemic death during acute myocardial infarction (AMI) and enhances the survival of cardiomyocytes exposed to oxidant stress." (PMID 23484149, 2013). "The HGF group had significantly more capillaries in the myocardial infarct (41.10±17.52/mm2) and peri-infarct (68.20±23.14/mm2) zones than that in control group (22.20±12.56, 41.75±15.11/mm2) (P<0.01)." (PMID 23301013, 2013). "The reduction of the infarct size and increase of the left ventricular ejection fraction were observed in a rat model when HGF was administered directly after acute myocardial infarction." (PMID 23407679, 2013). "Many studies have shown that acute myocardial infarction, ischemia reperfusion injury, and congestive heart failureinduce the expression of HGF in the heart." (PMID 23484149, 2013). "In the HGF group, the myocardial infarct and peri-infarct zone had higher HGF expression compared with the normal zone (P<0.01), and the normal zone was lowest in each of the three myocardial zones (P<0.01)." (PMID 23301013, 2013).